RASA2 (RAS p21 protein activator 2)
Diseases named in the same sentence as RASA2 in open-access papers (continued):
Sharing a sentence is not in itself a finding about the gene and the disease.
tumor (continued). "As seen with the TCR T cell model, RASA2-edited CAR T cells continued to kill target cells efficiently following repeated cancer cell exposures, whereas the control-edited CAR T cells were unable to control tumour cell growth." (PMID 36002574, 2022). "Overall, these data demonstrate that RASA2 can be ablated in CAR T cells to improve anti-tumour efficacy and survival with no apparent increased safety risk in this preclinical model using TRAC CAR T cells." (PMID 36002574, 2022). "These mutations may occur in receptors (e.g., KITKIT), effectors (BRAF, NRAS), or inhibitors (NF1, RASA2, CDKN2A, SPRED1) of the pathway, leading to proliferation of transformed melanocytes, abnormal differentiation, and persistent survival with impaired apoptosis of tumour cells." (PMID 41295253, 2025).
cancer (6 papers, 2017 to 2024). A tumor composed of atypical neoplastic, often pleomorphic cells that invade other tissues. "RASA2-deficient T cells exhibited increased activation, cytokine production, and metabolic activity and demonstrated a marked advantage in persistent cancer cell killing during repeated tumor antigen stimulation." (PMID 38516299, 2023). "We further tested whether RASA2-deficient T cells exhibit increased in vitro killing of cancer cells under these immunosuppressive conditions." (PMID 36002574, 2022). "In the protein network analysis, we found a network (SCAF11-ARID2-RASA2-ZBTB38) centered in RASA2, together with the chromatin remodeling factor ARID2, also mutated in various cancer types." (PMID 38892353, 2024). "In contrast to control-edited T cells that showed a gradual decline in the ability to control the growth of cancer cells with each stimulation, RASA2-ablated T cells maintained their robust killing capacity after multiple stimulations." (PMID 36002574, 2022). "Instead, RASA2 KO conferred a more persistent cancer killing capacity to T cells through repeated cancer antigen exposures." (PMID 36002574, 2022). "RASA2 ablation boosted cancer cell killing by TCR T cells compared with control-edited T cells across this range of suppressive conditions." (PMID 36002574, 2022). "In summary, RASA2 ablation limits dysfunction from chronic cancer antigen exposure across an array of diverse phenotypic metrics." (PMID 36002574, 2022). "Together, our findings highlight RASA2 as a promising target to enhance both persistence and effector function in T cell therapies for cancer treatment." (PMID 36002574, 2022). "Although T cells with RASA2 ablation had a moderate advantage in our cancer cell-killing assay upon first stimulation, this advantage became even more marked after multiple stimulations." (PMID 36002574, 2022). "We previously identified RASA2 as a gene target that boosts T cell proliferation and in vitro cancer cell-killing capacity when it is knocked out13." (PMID 36002574, 2022). "Collectively, these results show that T cells repeatedly exposed to their target antigen gradually lose the ability to control cancer cell growth, whereas ablation of RASA2 can render both TCR T and CAR T cells resistant to this dysfunctional state." (PMID 36002574, 2022). "RASA2-edited TRAC CD19-specific CAR T cells were co-cultured repeatedly with CD19-expressing cancer cells." (PMID 36002574, 2022). "Preclinical models of T-cell receptor and CAR-T therapies confirmed that RASA2-knockout CAR-T cells prolonged survival in mice xenografted with liquid or solid tumors, highlighting RASA2 as a promising target to enhance persistence and effector function in T-cell therapies for cancer treatment." (PMID 38516299, 2023). "To profile transcriptional changes systematically in primary RASA2-KO T cells, we performed whole transcriptome RNA-sequencing (RNA-seq) analysis on either RASA2-KO or control edited antigen-specific T cells after 48 h of co-culture with target cancer cells." (PMID 36002574, 2022). "Next, we tested whether the cancer cell-killing capacity of RASA2-ablated T cells is affected by repeated exposure to tumour antigen." (PMID 36002574, 2022). "This killing advantage after repetitive stimulation was specific, as demonstrated by the lack of cancer cell killing when either RASA2-KO or control TRAC CAR T cells were co-cultured with antigen-negative cancer cells." (PMID 36002574, 2022). "Collectively, these data suggest that T cells lacking RASA2 are sensitized even to low antigen levels, which can enhance their ability to detect and kill antigen-dim cancer cells." (PMID 36002574, 2022).
RASA2 also shares sentences with these, for which no sentence is quoted: allergic disease (2 papers); Allergy (1); cardiovascular disease (1); hepatoblastoma (1); hypertrophic cardiomyopathy (1); LEOPARD syndrome (1); liposarcoma (1); lung carcinoma (1); multiple myeloma (1); multiple sclerosis (1); Myoclonus (1); neurofibromatosis type 1 (1); olfactory neuroblastoma (1); prion disease (1); Sézary Syndrome (1); thyroid cancer (1); urachal carcinoma (1).